SETDB2 (SET domain bifurcated histone lysine methyltransferase 2)
Diseases named in the same sentence as SETDB2 in open-access papers (continued):
Sharing a sentence is not in itself a finding about the gene and the disease.
SETDB2 also shares sentences with these, for which no sentence is quoted: acute leukemia (1 paper); autism (1); bladder cancer (1); colon cancer (1); diabetic kidney disease (1); Encephalopathy (1); head and neck cancer (1); lymph node metastasis (1); medulloblastoma (1); myeloid malignancies (1); prostate tumor (1).